MTOR (mechanistic target of rapamycin kinase)
Diseases named in the same sentence as MTOR in open-access papers (continued):
Sharing a sentence is not in itself a finding about the gene and the disease.
tumor (continued). "Studies have indicated that PI3K/AKT deactivation via eriocitrin can inhibit tumor initiation, progression, and angiogenesis by inhibiting phosphorylation of various downstream substrates such as mTOR." (PMID 38613124, 2024). "In conclusion, the deletion of ZAG can effectively block the PI3K/AKT/mTOR signaling pathway, thereby preventing tumor cell proliferation, EMT, and lipid production in CRC." (PMID 39711976, 2024). "The PI3K/Akt/mTOR pathway and its impact on MM cell survival and supporting tumor microenvironment have been described." (PMID 39769182, 2024). "Although the anti-tumor effect of mTOR signaling and chemokine/receptor axis in mediating immune cells or tumor cells is two-sided, whose effect it has remains an open question." (PMID 38755125, 2024). "Investigations on the activity of Src Homology 2 domain-containing phosphatase-2 (SHP-2) and the PI3K/AKT/mTOR signaling cascade within the tumor tissues were also conducted through Western Blot analysis." (PMID 38967628, 2024). "The first clinical anti-tumor observation of the mTOR inhibitor, the immunosuppressive drug rapamycin, was detected in the treatment of post-transplant kidney cancer." (PMID 38515456, 2024). "Apolipoprotein C-II regulates lipid metabolism, and its interaction with CD36 promotes tumour progression via PI3K/AKT/mTOR signalling, which regulates the EMT process." (PMID 38974022, 2024). "Classification, highest clinical phase, status, and application of PI3K/Akt/mTOR inhibitors in various tumor types based on the GlobalData database." (PMID 38515456, 2024). "For example, upregulation of the PI3K/AKT/mTOR pathway has been identified as a driver of sorafenib resistance, promoting tumor cell survival and proliferation despite treatment." (PMID 39682093, 2024). "The phosphoinositide−3−kinase/AKT/mTOR signaling pathway is critical to tumor development and metastasis and important in MYC regulation." (PMID 38785546, 2024). "To study the clinical relevance of LAMP2a and RNH1, we detected the expression of LAMP2a, RNH1, and mTOR in a tissue microarray containing 94 CRC tumor and 88 normal tissue samples, by means of multiplex immunohistochemistry staining." (PMID 39513392, 2024). "A higher mTOR exon 8 skipping was observed in tumor tissues compared to matched normal tissues, showing a negative correlation with SF3B3 expression." (PMID 38671459, 2024). "LAT1 facilitates the uptake of large neutral amino acids, such as leucine, which are essential for the activation of the mTOR signaling pathway, promoting tumor growth and proliferation." (PMID 39766159, 2024). "Our RNA sequencing data also show significant alterations in immune and tumor-related pathways, including downregulation of Th1/Th2 cell differentiation and mTOR signaling." (PMID 39091728, 2024). "The modulation of the mTOR signaling pathway has also been suggested to contribute to the immune features of the tumor microenvironment and facilitate antitumor immune responses based on preclinical and clinical data." (PMID 38791040, 2024). "Several inhibitors targeting the PI3K/AKT/mTOR pathway have been investigated for their anti-tumor effects in both clinical and preclinical studies in the treatment of MM." (PMID 38961036, 2024). "Some in vitro and animal studies have shown the effects of inhibition of PI3K/Akt/mTOR pathway on reducing tumor cell viability and GH secretion in somatotroph PitNETs." (PMID 39224564, 2024). "These tumour clones provoke expansion and apoptosis in surrounding cells by activating the nutrient sensor mTOR." (PMID 39682725, 2024).
tumor (continued). "Overexpression of miR-1224-5p targets PLK1, reduces the phosphorylation of PI3K, Akt, and mTOR, and negatively regulates the PI3K/Akt/mTOR pathway, and inhibits tumor growth and EMT." (PMID 39119480, 2024). "GRIK3, encoding the glutamate receptor, is crucial in synaptic transmission and implicated in tumor-related pathways like MAPK/ERK and mTOR." (PMID 38534332, 2024). "Further studies revealed that mTOR activators abolished the inhibitory effect of Puerarin on PC cells, suggesting that mTOR plays a crucial role in the anti-tumor effect of Puerarin on PDAC." (PMID 39650709, 2024). "In mice, combined EGCG with tamoxifen leads to a decrease in tumor volume by 71% and tumor weight by 80% by inhibiting mTOR and EGFR expression." (PMID 39725830, 2024). "Inhibitors of the PI3K/AKT/mTOR signaling pathway suppress c-Myc translation, thereby reducing tumor levels of c-Myc in a mouse tumor model." (PMID 38982480, 2024). "On the contrary, mTOR can regulate the formation of stress granules through its downstream molecules, which leads tumor cells to resist to external stress." (PMID 38238825, 2024). "In HCC, activation of mTOR leads to increased cell proliferation and survival, angiogenesis, and decreased apoptosis, all of which contribute to tumor growth and metastasis." (PMID 38468074, 2024). "This suggested that high UPP1 expression in tumor cells contributed to the upregulation of PD-L1 through the PI3K/AKT/mTOR pathway." (PMID 38331898, 2024). "New therapeutic regimens are currently being investigated to increase the efficacy of mTOR inhibitors in inhibiting tumor progression and improving survival." (PMID 38339294, 2024). "Transcriptional analyses of metformin-treated mouse bone marrow-derived macrophages show decreased expression levels of pro-tumour genes, including Tgfbi and Il1β, related to enhanced mTOR/HIF1α signalling and metabolic rewiring towards glycolysis." (PMID 39315158, 2024). "This approach has shown promising outcomes in animal models, suggesting that modulating mTOR signal is a potential method to enhance anti-tumor immunity in GBM." (PMID 38720342, 2024). "This research has shown that activating the mTOR and NFκB pathways is crucial for controlling the inhibitory impact of tumor-initiating cells in this tumor model." (PMID 38691208, 2024). "Common oncogenic alterations in PI3K, AKT, and PTEN can activate the mechanistic target of rapamycin (mTOR), thus inhibiting autophagy and enhancing tumorigenesis, while tumor suppressors activate autophagy by negatively regulating mTOR and AMPK." (PMID 38741166, 2024). "The mIHC results of subcutaneous tumor tissues indicated a significantly lower expression of phosphorylated Akt proteins (Ser473 and Thr308) and phosphorylated mTOR proteins (Ser2481 and Ser2448) in oe-PLCG2+MK2206 group in contrast to oe-PLCG2 group." (PMID 39494327, 2024). "Here, we used 3D imaging to evaluate the expression of pS6, a downstream effector of the PI3K/AKT/mTOR pathway and a tumor marker, in intact UTUC samples." (PMID 39133649, 2024). "Distinct from therapies that primarily target adaptive immunity or the tumor cells directly, our study advances our understanding of the fundamental principles of mTOR signaling that govern macrophage-mediated tumor cell phagocytosis." (PMID 39766137, 2024). "Such evidence suggests that G-CSF primes the PI3K/AKT/mTOR signaling pathway by curtailing SHP2 expression in the tumor-affiliated macrophages." (PMID 38967628, 2024). "The PI3K/AKT/mTOR pathway is particularly significant, with mutations in PIK3CA commonly associated with venous and lymphatic malformations but can be also found in tumour endothelial cells." (PMID 39608012, 2024). "In contrast, PIK3R1 (p85α regulatory subunit of PI3K) is a tumor-suppressor gene, and the protein p85α has a reduced capacity to restrain p110α when PIK3R1 is mutated, resulting in activation of PI3K-Akt-mTOR pathway." (PMID 39334689, 2024).
tumor (continued). "EGCG, the principal catechin in green tea, has been shown to inhibit the PI3K/AKT/mTOR and NF-κB signaling pathways, thereby suppressing tumor cell proliferation and inducing apoptosis." (PMID 39650709, 2024). "Microglia can be affected by astrocyte-secreted STAT3 as well as tumor-secreted mTOR, MAPK, and NFκB." (PMID 38243240, 2024). "In case of a patient developing a tumour during IS therapy, the use of mTOR inhibitors should be considered." (PMID 38341510, 2024). "When combined with rapamycin, RSV inhibits tumor growth by modulating the PI3K/AKT/mTOR signaling pathway." (PMID 39439517, 2024). "ECM components and the PI3K-Akt-mTOR signaling pathway play crucial roles in processes related to tumor progression, including cell proliferation, adhesion, invasion, and migration." (PMID 39456581, 2024). "Traditionally, pharmacological mammalian/mechanistic targets of rapamycin (mTOR) kinase inhibitors have been used during transplantation and tumor treatment." (PMID 38873415, 2024). "Those that are overexpressed in OS tissues, enhance tumor progression or drug resistance by promoting PI3K/Akt/mTOR pathway signaling; while, those that are downregulated in tumor tissues, inhibit tumor progression by inhibiting the PI3K/Akt/mTOR pathway." (PMID 39119480, 2024). "Nevertheless, mTOR which is improperly stimulated in tumor cells sends out signals that trigger tumor cells to proliferate, spread, and infiltrate healthy tissues located nearby or far from it." (PMID 38965615, 2024). "Everolimus is an mTOR inhibitor that suppresses the pro-osteoclast paracrine pathway of tumor cells, thereby inhibiting bone metastasis." (PMID 39148909, 2024). "Collectively, FKC inhibits glucose metabolism and tumor angiogenesis in NPC by targeting the HSP90B1/EGFR/PI3K/Akt/mTOR signaling axis." (PMID 38711062, 2024). "This different receptor behavior can be explained by its higher kinase activity and its ability to activate pro-oncogenic pathways, including the PI3K/Akt/mTOR, and rewire tumor metabolism, thus supporting and enhancing tumor growth in vitro and in vivo." (PMID 39195235, 2024). "Hyperactivation of the phosphatidylinositol 3-kinase/protein kinase B/mammalian target of rapamycin (PI3K/AKT/mTOR) pathway is one of the common mechanisms leading to tumor resistance." (PMID 38317230, 2024). "By degrading PIP3, PTEN effectively counterbalances the activation of the oncogenic PI3K/AKT/mTOR signaling pathway, exerting profound effects on tumor cell cycle progression, apoptosis, tumor invasiveness, and angiogenesis." (PMID 39688352, 2024). "These interactions activate signaling pathways like PI3K/AKT/mTOR and TGFβ, promoting tumor progression." (PMID 38230205, 2024). "In the last few decades, various clinical trials have shown prospective anti-tumor therapies targeting the PI3K/AKT/mTOR pathway." (PMID 38980538, 2024). "It activates AMP-activated protein kinase (AMPK), which inhibits the mammalian target of rapamycin (mTOR) pathway, thereby suppressing tumor cell growth and proliferation." (PMID 39597914, 2024). "The mTOR inhibitor blocks signaling producing positive effects of anti-inflammatory, anti-tumor cell proliferation, and inducing apoptosis." (PMID 38755125, 2024). "Based on the results obtained from the functional enrichment analysis above, we took into account the vital roles that the "PI3K-Akt signaling pathway" and "mTOR signaling pathway" played in regulating tumor fate and signal transduction." (PMID 39494327, 2024). "In the TME, this drug seems capable of decreasing malignancy-associated factors, increasing the production of pro-inflammatory cytokines, and inhibiting the tumor-inducing AKT/mTOR pathway." (PMID 39339165, 2024). "On the contrary, other signature genes (e.g., EIF4E, MAP4K1) were shown to be highly expressed in tumor samples, supported by their functions in either mTOR or Hippo regulations." (PMID 38468074, 2024).
tumor (continued). "Concurrently, the increase in phospho-PTEN suggests enhanced PTEN activity, which negatively regulates the PI3K/Akt/mTOR pathway, thereby inhibiting mTOR signaling and potentially reducing tumor growth and progression." (PMID 39125671, 2024). "Most intriguingly, 5 mg/kg sepantronium bromide therapy in tamoxifen-induced double knock-out mice for TGFBR1 and PTEN limits tumor growth and mTOR phosphorylation at Ser-2448 and SQSTM1/p62 immunohistochemistry." (PMID 39595208, 2024). "Along these lines, we showed that PRT1419 and PRT2527 combine with and enhance the anti-tumor effects of TKIs (Sunitinib, Pazopanib, Cabozantinib), mTOR inhibitors (Everolimus) and HIF2a inhibitors (Belzutifan)." (PMID 38371625, 2024). "The DEPs participated in numerous oncogenic pathways, PI3K/AKT/mTOR cell signaling, and the silencing of several tumor suppressors, such as PTEN and RBL1, during tumorigenesis." (PMID 38672200, 2024). "These tumours have alterations in chromosomal numbers and are associated with mutations in MET, CDKN2A, SETD2, BAP1, PBRM1, NFE2L2, and mTOR genes and have a better prognosis when compared with clear cell RCC in the organ-confined stage." (PMID 38265103, 2024). "LAMP2a‐mediated CMA‐selected degradation of specific substrate is key for tumor progression, we therefore screened for the LAMP2a substrates that are responsible for aripiprazole‐induced mTOR and CRC inhibition." (PMID 39513392, 2024). "Inhibitors against PI3K, AKT, and mammalian target of rapamycin (mTOR) have remarkable effects on tumor cell proliferation and radiotherapy sensitization in cell cultures and mouse models." (PMID 38819439, 2024). "The data revealed an upregulation of Beclin1 and a downregulation of mTOR in tumor tissues compared to the control condition." (PMID 38164366, 2024). "miR‐148a targets AKT2, inhibiting its expression and activity, subsequently suppressing the activation of downstream mTOR, ultimately leading to the inhibition of tumor cell growth." (PMID 39092291, 2024). "In the terms of mechanism, inhibition of HDAC7 induces remarkably decrease at the levels of p‐AKT and p‐mTOR, which is extremely important for tumour progression, resulting in arresting of cell proliferation and invasion." (PMID 39431349, 2024). "PIK3CA, a linchpin in the PI3K/AKT/mTOR pathway, significantly influences tumor tropism by modulating chemokines, growth factors, and extracellular matrix (ECM) interactions." (PMID 39369580, 2024). "The mTOR complex plays a critical role not only in gene transcription regulation and tumor metabolism but also in the regulation of autophagy and apoptosis." (PMID 39145305, 2024). "Not only the Akt/mTOR pathway but also other pro-oncogenic or tumor-suppressive pathways have been related to ChREBP." (PMID 39518998, 2024). "These proteins form a tumor-suppressor complex crucial for the inhibition of the mammalian target of rapamycin (mTOR) pathway, a signaling cascade integral to cellular growth, proliferation, and survival." (PMID 39727664, 2024). "We showed that genetic suppression of MTOR significantly reduced tumor cell phagocytosis compared to that in the control knockdown group, consistent with the results of the pharmacological inhibition of the mTOR pathway." (PMID 39766137, 2024). "Estrogen signaling can activate the PI3K/AKT/mTOR pathway, leading to further promotion of tumor growth and survival." (PMID 38666020, 2024). "Each of these steps and interactions underscores the complexity and importance of the PI3K/AKT/mTOR signaling pathway in the context of oncology, particularly in its role in promoting tumor growth and survival." (PMID 38473413, 2024). "miR‐122 indirectly promotes the activation of the PI3K/AKT/mTOR pathway by suppressing the expression of tumor suppressor genes, such as SPRY2, thereby relieving the inhibition of the Rat sarcoma (Ras)/mitogen‐activated protein kinase (MAPK) pathway." (PMID 39092291, 2024).
tumor (continued). "The PI3K/AKT/mTOR (PAM) signalling pathway is pivotal in supporting tumour growth and progression by orchestrating cell cycle activities and regulating the synthesis of macromolecules such as proteins, nucleotides, and lipids." (PMID 39568072, 2024). "Arbutin essentially hinders tumor PD-L1 expression by orchestrating changes in the AKT/mTOR signaling pathway." (PMID 39628695, 2024). "While the dysregulation of PTEN disturbs PI3K/AKT/mTOR signaling, its inactivation can lead to gene instability and thus induce the formation of tumor neoantigens." (PMID 38672200, 2024). "The tumor subsequently decreased in size from 12 mm to 7.7 mm with mTOR inhibitor treatment, but ventricular enlargement remained unchanged." (PMID 39040610, 2024). "Combinational therapy is a recent approach that targets multiple pathways associated with cancer development, such as PI3K/AKT/mTOR and RAF/MEK/ERK, by focusing on tumor cell receptors." (PMID 38785748, 2024). "Treatment strategies are based on the individual disease characteristics and are therefore highly diverse, including, e.g. antiseizure medication as well as tumor surgeries or treatments with mTOR inhibitors." (PMID 38459571, 2024). "Apoptosis of tumor cells was associated with augmented expression of TNF-α, Fas, and FasL, as well as suppression of the anti-apoptotic NF-κB and mTOR pathways." (PMID 39683650, 2024). "Anesthetics have been reported to affect autophagy and subsequently tumor progression by mediating mTOR signaling." (PMID 38482052, 2024). "When aberrantly expressed, LAT1-4F2hc mediates the uptake of leucine and tunes the growth of tumour cells through the mechanistic target of rapamycin (mTOR) pathway, implicating the transporter in several human malignancies." (PMID 38697966, 2024). "PI3k/Akt/mTOR signal pathway is an important signal transduction pathway that regulates cell growth, which is vital in tumor occurrence, development, invasion, migration, and therapeutic resistance." (PMID 38645502, 2024). "Many studies have reported that mTOR is abnormally activated in tumor cells, thereby promoting the growth, proliferation and metastasis of tumor cells 35-37." (PMID 38817860, 2024). "The PI3K/PDK1/mTOR/SGK pathway has been shown to compensate for the function of the PI3K/AKT pathway in the promotion of tumor survival, progression, migration, and drug resistance." (PMID 38334632, 2024). "The induced free radicals reduce the resistance induced by hypoxia in an Akt-mTOR pathway-dependent manner, and enhance the tumor’s radiation killing sensitivity to action." (PMID 39128942, 2024). "It was suggested that schisandrin A can inhibit the PI3K/AKT/mTOR signaling pathway in tumor tissues." (PMID 38452391, 2024). "Previous studies have demonstrated that inhibiting the PI3K/AKT/mTOR pathway can effectively suppress inflammatory responses and oxidative stress, alleviating tumor progression." (PMID 39857585, 2024). "PD-L1 can activate the activated protein kinase B (AKT)/mammalian target of the rapamycin (mTOR) pathway within tumor cells, enhancing their survival and growth." (PMID 39628695, 2024). "Beyond the molecular work-up including methylome profiling and panel sequencing of tumor material, Phospho-mTOR-IHC was applied on tumor samples to detect mTOR activation." (PMID 38334907, 2024). "Lycorine and lycorine hydrochloride demonstrated anticancer effects through the regulation of multiple signaling pathways in tumor cells, including mTOR, NF-κB, JNK/STAT3, and ERK, among others." (PMID 39245716, 2024). "Our results indicate that arbutin regulates PD-L1 expression in tumor cells by targeting the AKT/mTOR pathway." (PMID 39628695, 2024).